XIAP (X-linked inhibitor of apoptosis)
Diseases named in the same sentence as XIAP in open-access papers (continued):
Sharing a sentence is not in itself a finding about the gene and the disease.
tumor (continued). "Studies have found that some Inhibitors of Apoptosis protein (IAPs) like XIAP, cIAP1, cIAP2, and survivin are released into the extracellular spaces by tumor and normal cells via sEVs and are uptaken by neighboring tumor microenvironments as a preventative measure against cell death." (PMID 38596136, 2024). "In contrast to cIAP1, cIAP2 and XIAP, Survivin and Livin are largely tumor-specific." (PMID 36845731, 2023). "Previously, miR-618 was shown to play a role in tumor inhibition by targeting XIAP expression." (PMID 37342185, 2023). "As putative explanation, XIAP might constantly inhibit constitutive background apoptosis signaling from inside or outside the tumor cell, preventing, for example, “death by default”." (PMID 36416169, 2023). "XIAP could induce the resistance to apoptosis, providing survival advantage to the metastatic tumor cells." (PMID 37534104, 2023). "Conversely, several reports also depicted XIAP as a tumour suppressor, among which a study revealed that caveolin‐1‐mediated XIAP recruiting to the α‐integrin complex could suppress cell migration and enhance cell adhesion." (PMID 37154878, 2023). "Also, a significant correlation between higher levels of XIAP and tumor differentiation, venous invasion and Duke’s staging was found." (PMID 35406442, 2022). "In the present study, BDMC significantly inhibited the tumor growth of GBM 8401 xenograft mice in vivo via upregulating the expression of BAX (pro-apoptotic factor) and caspase-3 and downregulating the expression of Bcl-2 (anti-apoptotic factor) and XIAP in tumor tissues." (PMID 35008959, 2022). "XIAP is highly expressed in 60 human tumor cell lines of the National Cancer Institute." (PMID 35992856, 2022). "AITC effectively suppressed protein expressions of MCL-1, MMP-9, VEGF, and XIAP in the tumor area." (PMID 36142326, 2022). "In addition, Western blotting was carried out to detect the protein expression levels of p-p65, c-myc, XIAP, Bcl-2 and cleaved caspase-3 in tumor tissues." (PMID 35541911, 2022). "The X-linked inhibitor of apoptosis (XIAP)-associated factor 1 (XAF1), also found in Omy27, is a regulator of cytokinesis that considerably increases stress-induced apoptosis and decreases the invasive capacity of tumor cells." (PMID 36672855, 2022). "In addition, this study revealed that different tumor-infiltrating immune cells were correlated with XIAP in LUAD-BM, and constructed the SBF2-AS1 or RUNDC3A-AS1-has-miR-338-3p-XIAP network." (PMID 35992856, 2022). "Similarly, analysis of XIAP and Smac in 66 RCC indicated a tumor stage-dependent increase of XIAP expression with a disturbed ratio of XIAP versus Smac." (PMID 34384473, 2021). "Herein, our findings also showed that XIAP might be one of the mechanisms for reduced tumor volumes and weight in the GBM 8401 cell xenograft tumor mice model." (PMID 34071132, 2021). "Because our results suggest a dual function of A4 as an inhibitor of both XIAP and Bcl-2, it may be effective against a wide range of tumours over-expressing either one or both these proteins." (PMID 32587235, 2020). "Elevated XIAP protein level promotes tumor invasion and metastasis." (PMID 33138314, 2020). "In addition, the absence of Sept4/ARTS gene can also increase the number of hematopoietic stem cells and progenitor cells, increase XIAP levels, enhance apoptosis, and accelerate tumor development." (PMID 32398959, 2020). "These mice exhibit spontaneous accelerated tumor development and elevated XIAP levels." (PMID 32182843, 2020). "The finding of this research revealed that XIAP may have a number of other biological functions in addition to participating in the mechanism of apoptosis, suggesting its potential value in tumor gene therapy." (PMID 32537125, 2020).
tumor (continued). "An early study showed that in vitro and in vivo radiosensitization of colorectal cancer HT-29 cells by JP1201 decreased the survival of HT-29 cells and tumor growth via an additive effect in apoptosis, as well as a reduction in the level of XIAP and an impairment of DNA repair mechanisms." (PMID 32325691, 2020). "In tumours with low ATM levels, XIAP high/PTEN low tumours have improved PFS (p = 0.030)." (PMID 31635307, 2019). "Tumor cells with pathologically elevated XIAP levels are known to be more resistant to radio- or chemotherapy by reducing the capability to undergo therapy induced cell death; it was already shown that reducing XIAP levels can re-sensitize cells to therapy induced apoptosis." (PMID 31151416, 2019). "The changes of tumor volume, body weight, NF‐κB activation, MAPK activation, and tumor progression‐associated proteins (MMP‐9, XIAP, VEGF, and Cyclin‐D1) after regorafenib treatment were evaluated with digital caliper, digital weight, and ex vivo Western blotting assay." (PMID 30801954, 2019). "Considering the relative high expression of XIAP and circ0005276 in PCa tissues with advanced tumor stage and metastasis, we hypothesized that they might be two oncogenes in PCa progression." (PMID 31624242, 2019). "It has been reported that XIAP protein expression was significantly correlated with a more aggressive tumor phenotype and decreased overall and disease-free survival, suggesting a prognostic value of XIAP for invasive ductal breast cancer with triple-negative phenotype." (PMID 30627061, 2018). "Furthermore, the tumor and apoptosis phenotypes of Sept4/ARTS‐deficient mice are suppressed by inactivation of XIAP, indicating that this protein is a major physiological target for the pro‐apoptotic and tumor suppressor activity of ARTS." (PMID 29460395, 2018). "PEITC also inhibited tumor growth by inhibiting XIAP in our GBM 8401 ectopic xenografts in vivo." (PMID 30201893, 2018). "Thus, it will be of great interest to further explore how the ARTS/XIAP apoptotic module is implicated in driving ISC-dependent tumor initiation, CSC niche maintenance and tumor replenishment." (PMID 30389919, 2018). "CRNDE is enriched in the stem-like population of GBM cells and promotes tumor cell proliferation and migration and by sponging down miR-186 to derepressing the expression of XIAP (X-linked inhibitor of apoptosis) and PAK7 [p21 protein- (Cdc42/Rac-) activated kinase 7], two prooncogenic molecules." (PMID 30116729, 2018). "In the present study, the expression of XIAP decreased significantly in cells treated with shikonin, especially those cotreated with TRAIL, suggesting that XIAP downregulation may increase tumor sensitization to TRAIL." (PMID 30594131, 2018). "Hence, XIAP expression contributes to a more resistant tumour with a lower response to adjuvant radiation therapy." (PMID 28486965, 2017). "MiR-212 exerted its tumor suppressive roles in RCC by targeting XIAP." (PMID 29190902, 2017). "Knockdown of survivin and XIAP markedly reduced cell proliferation and tumor growth." (PMID 28039474, 2017). "Importantly, NF-κB activation via the survivin-XIAP complex has been shown to induce tumor cell invasion and formation of metastasis." (PMID 28039474, 2017). "In addition, knockdown of survivin or XIAP was accompanied by a pronounced decrease in tumor cell proliferation of NEC tumors as assesed by Ki-67 staining." (PMID 28039474, 2017). "Furthermore, forced expression of XIAP 3′UTR increased cell proliferation in the tumor, as determined by immunohistochemical analysis of nuclear incorporation of Ki-67, and also decreased cell apoptosis as determined by TUNEL assay." (PMID 28186968, 2017). "It was reported that miR-200c-3p could target XIAP, thereby leading to decreased levels of XIAP and cell viability; tumor cells were more resistant to the apoptosis induced by 5-FU, when they express higher levels of XIAP." (PMID 28535802, 2017).
tumor (continued). "XIAP play important roles in tumor behaviors and chemosensitivity of ATC cells." (PMID 29221164, 2017). "Furthermore, NFκB and XIAP expression were observed to be significantly higher in tumor embolic structures in IBC patient tumor tissue." (PMID 28460441, 2017). "Finally, we evaluated the impact of XIAP on tumor formation in vivo using an ATC xenograft mouse model." (PMID 29221164, 2017). "Immunohistochemical analysis of IBC patient tumor samples with documented tumor emboli revealed high NFκB (p65) staining along with expression of XIAP, a potent anti-apoptotic protein known to interact with NFκB signaling in enhancing survival of malignant cells." (PMID 28460441, 2017). "Thus, we focused on Inhibitor of apoptosis protein (IAP) family members survivin and XIAP that orchestrate inhibition of apoptosis, induce resistance against chemotherapeutics and facilitate tumor metastasis." (PMID 28039474, 2017). "Additionally, our data also showed that XIAP knockdown ATC-xenografted nude mice have inhibited tumor growth." (PMID 29221164, 2017). "Moreover, co-transfection of cells with miR-23a mimics and the XIAP expression plasmid demonstrated that expression of XIAP significantly abrogated miR-23a mimic-promoted tumor cell migration and invasion." (PMID 29113338, 2017). "The effect of XIAP on tumorigenesis was evaluated using a xenograft tumor model with nude mice." (PMID 29221164, 2017). "Importantly, the overexpression of XIAP independently is insufficient to stabilize endogenous BIRC3 implying that increased expression of BIRC3 must also occur to facilitate tumor growth and progression." (PMID 27074575, 2017). "Together, our results imply that XIAP is critical for tumor progression and chemoresistance of ATC." (PMID 29221164, 2017). "In general, cIAP1, XIAP and survivin mRNA and protein were highly expressed in most tumor types." (PMID 27167336, 2016). "The western blot results revealed that EF24 decreased the expression of XIAP and increased the expression of cleaved caspase-9 and caspase-3.The positive tumor cells for Ki-67, a cell proliferation marker, were substantially less in tumors treated with EF24, compared with control tumors." (PMID 27571770, 2016). "XIAP and p65 proteins localize largely to the epithelium, and are sparse in the tumor stroma." (PMID 25686839, 2015). "Patients with resistant tumours highly expressing XIAP may benefit from alternative treatment strategies, such as Smac mimetics post neoadjuvant radio chemotherapy." (PMID 26071313, 2015). "As well as contributing to disease progression, XIAP was also reported to contribute to chemotherapy resistance, and targeting this protein was found to effectively sensitise cells to apoptosis and suppress tumour progression." (PMID 26071313, 2015). "We found that XIAP levels in tumour tissue increased as chemo resistance grades progressed from RCPath A, through RCPath B, to RCPath C, suggesting XIAP may play a critical role in resistance to neoadjuvant radio chemotherapy." (PMID 26071313, 2015). "Since XIAP is highly expressed in NSCLC tumours, it might be involved in suppression of apoptosome activity in these tumours." (PMID 24626292, 2014). "Silencing xIAP or cIAP1 significantly increased the tumor cell to FasL-induced apoptosis." (PMID 24422988, 2014). "Therefore, it is possible that LCL85 sensitizes tumor cells to Fas-mediated apoptosis at least in part through inducing C16 ceramide accumulation, resulting in ceramide-mediated xIAP and cIAP1 proteasomal degradation." (PMID 24422988, 2014). "By contrast, the presence of XIAP in the xenograft tumor mass decreased with NSC745885 treatment." (PMID 25127132, 2014). "It has been shown that CDK2-dependent expression of anti-apoptotic protein XIAP may account for the inefficient apoptosis in tumor cells including Bcr-Abl expressing cells." (PMID 25360622, 2014).
tumor (continued). "To test whether the inactivation of XIAP can enhance the activity of apoptosome apparatus in cytosol from NSCLC tumours, we used the XIAP-neutralizing peptides AVPIAQK (P1) and ATPFQEG (P2)." (PMID 24626292, 2014). "We found that HM90822B significantly inhibited the expression of XIAP and survivin, reduced cell growth in NSCLC cells, especially cells harboring mutated EGFR, and resulted in tumor regression in xenograft mice originated with these cells, such as HCC827 and PC-9 cells." (PMID 25321484, 2014). "Moreover, TQ was found to increase p-p38 protein expression in tumor tissues, with down-regulation of XIAP, survivin, Bcl-xL and Bcl-2 anti-apoptotic gene products." (PMID 24098377, 2013). "This study first defines the in vitro quantitative analysis of XIAP expression in radiation-induced tumour cells and its relation with the radiation tolerance of tumours and finds that tumour cells with a strong radiation resistance have relatively high XIAP expression." (PMID 24336110, 2013). "XAF1 (XIAP-associated factor 1) is a novel XIAP binding protein which could disturb the combining of XIAP with caspases, abolishes its protection on tumor cells and results in tumor cell apoptosis." (PMID 23826230, 2013). "The ANTP-SmacN7 fusion protein could enter and accumulate in cells; in vitro XIAP expression of radiation-induced tumour cells was negatively correlated with tumour radiosensitivity." (PMID 24336110, 2013). "It is thought that this induced resistance in a wide variety of tumor cells occurs via induction of NF-κB effector genes, including Bcl-2, Bcl-xL, survivin, XIAP, c-IAP1 and c-IAP2 that are known to mediate protective responses to chemotherapeutic agents and radiation." (PMID 23437404, 2013). "Furthermore, XIAP protein expression is positively correlated with cell viability after irradiation, indicating that the decrease in the radiosensitivity of tumour cells is related to an increase in XIAP expression." (PMID 24336110, 2013). "First, a TRAIL-induced activation of NF-кB could mediate the transcription of antiapoptotic targets such as XIAP and cFLIP, protecting the tumour from proapoptotic stimuli and permitting proliferation and metastasis." (PMID 23937794, 2013). "The expression of each IAP group was a significant independent prognostic marker for recurrence-free survival (PcIAP1-N+Survivin-N=0.016; PcIAP1-C+cIAP2+XIAP=0.029; PSurvivin-C+Livin=0.032), in addition to the presence of muscle-invasive disease and high tumor grade." (PMID 23599779, 2013). "In addition, a decrease in XIAP expression following single or combination treatments was observed in SW620 TRAIL-resistant tumor cells." (PMID 23852390, 2013). "Down-regulation of XIAP by siRNA could significantly suppress proliferation of tumor cells and sensitize tumor cells to chemotherapeutic agents." (PMID 22043320, 2011). "Moreover, we have identified a novel TGFβ tumor suppressor pathway that acts directly on a known cell survival mechanism that responds to stress with the survivin/XIAP dependent inhibition of caspases that effect apoptosis." (PMID 21559296, 2011). "A two-fold increase in XIAP mRNA levels was observed in tumor tissue." (PMID 21483830, 2011). "Moreover, we have identified a novel TGFβ/PKA tumor suppressor pathway that acts directly on a known cell survival mechanism that responds to stress with the survivin/XIAP dependent inhibition of caspases that effect apoptosis." (PMID 21559296, 2011). "Based on this background and the current findings regarding AKAP-PKA transduceome signaling in XIAP downregulation, we hypothesized that the tumor suppressor effects of TGFβ can be mediated through the TGFβ/PKA signaling axis." (PMID 21559296, 2011). "The reported differences in phenotype upon XIAP knockdown for a given tumor cell line could be a function of degree and or duration of knockdown, the methodology for quantifying viability, or a more subtle parameter such as cell-culture conditions." (PMID 20067634, 2010).
tumor (continued). "Second, in tumor cells caspases might be kept in check by cellular caspase inhibitors such as c-FLIP or XIAP." (PMID 24281211, 2010). "Together these data suggest that XIAP-targeting drugs could be particularly effective in tumours in which XIAP function is unopposed because the regulatory mechanisms are inactivated." (PMID 20485285, 2010). "However, there is controversy regarding XIAP's role in regulating tumor cell proliferation and survival under normal growth conditions in vitro." (PMID 20067634, 2010). "As sensitisation of tumour cells to TRAIL can be achieved by downregulating XIAP, we asked whether a similar response could be induced in Me1007 cells, in spite of their low expression of caspase-8." (PMID 20461078, 2010). "According to this data, XIAP is thought to render tumour cells resistant to multi-agent chemotherapy through its ability to inhibit caspases, and, on this basis, has been proposed as an important adverse prognostic factor responsible for tumour chemoresistance." (PMID 20485285, 2010). "XIAP protein levels were monitored in 10 human tumor cell lines derived from different tumor types." (PMID 20067634, 2010). "It is possible that the associated stresses of in vivo tumor growth (e.g. hypoxia) generate a death signal (activated caspases) that is sufficient to render the tumor cells sensitive to inhibition of XIAP solely via the disruption of the caspase 9/XIAP interaction." (PMID 20067634, 2010). "Therefore, XIAP has been described and reviewed repeatedly as a chemoresistance factor in different tumour entities." (PMID 20485285, 2010). "Thus, the relative expression level of XIAP was significantly higher in poorly differentiated RCCs (G3) than in well and moderately differentiated tumours (G1 and G2; P=0.04)." (PMID 15328523, 2004). "Quite similarly, XIAP mRNA expression significantly increased with tumour dedifferentiation." (PMID 15328523, 2004). "Importantly, the relative XIAP mRNA expression levels significantly increased from early (pT1) to advanced (pT3) tumour stages (P=0.0002) and also with tumour dedifferentiation (P=0.04)." (PMID 15328523, 2004). "Importantly, RCCs infiltrating beyond the kidney (pT3) exhibited significantly higher relative XIAP mRNA expression levels when compared with tumours confined to the organ (pT1 and pT2; P=0.002)." (PMID 15328523, 2004). "Importantly, the compromised immune response through XIAP-inhibition did not further aggravate tumorigenesis, suggesting that loss of XIAP does not lead to tumor formation, as seen in XIAP patients." (PMID 36270981, 2022). "Thus, XIAP deubiquitination is required to reset its activity, and attenuation of XIAP may contribute to tumor suppressor function by inducing apoptosis." (PMID 36551253, 2022). "Consequently, loss of XIAP also did not impair tumor formation and did not prevent LCLs from spreading via the circulation into the spleen." (PMID 36270981, 2022). "Besides, the study demonstrated that an abnormally high expression of NQO1 would promote phosphorylation level of X-linked inhibitor of apoptosis protein (XIAP) and enhance stability of XIAP protein, thereby inducing tumor growth and inhibiting apoptosis in HCC." (PMID 33083480, 2020). "Therefore, we hypothesized that stress-mediated XIAP-NFκB signaling can lead to a tumor cell-promoted immunosuppressive environment and targeting this signaling axis can enhance the efficacy of immunotherapy." (PMID 30400822, 2018). "Compared to direct inhibition of NFκB activity, embelin, which potentiates apoptosis by relieving the inhibitory effect of XIAP on caspase 9 activity caused some increase in cell death, in particular in the interior of the spheroids although the tumor spheroid formation itself was not inhibited." (PMID 28460441, 2017). "Moreover, XIAP mediated the tumor suppressive roles of miR-212 in RCC." (PMID 29190902, 2017). "Thus we analyzed the protein level of XIAP in representative tumor samples (XAF1-M vs. XAF1-UM)." (PMID 28122345, 2017).